SOCS3 (suppressor of cytokine signaling 3)
Diseases named in the same sentence as SOCS3 in open-access papers (continued):
Sharing a sentence is not in itself a finding about the gene and the disease.
multiple sclerosis (11 papers, 2012 to 2025). A progressive autoimmune disorder affecting the central nervous system resulting in demyelination. "As an important negative regulator of cytokine signaling pathways, SOCS3 plays a vital role in a variety of inflammatory diseases, such as multiple sclerosis, experimental autoimmune encephalomyelitis, pain, and airway inflammation." (PMID 34804364, 2021). "Studies have found that in mice with experimental autoimmune encephalomyelitis (EAE, a murine model of multiple sclerosis), mmu-miR-409-3p targets suppressor of cytokine signaling protein 3 (SOCS3)." (PMID 32849505, 2020). "Further, SOCS3 expression in macrophages, microglia and dendritic cells is critical for deactivation of neuroinflammatory responses in an animal model of Multiple Sclerosis." (PMID 23226414, 2012). "Collectively, these data suggest that SOCS3 could represent an important therapeutic target for managing multiple sclerosis." (PMID 40755762, 2025). "The well-documented connection between decreased SOCS3 levels and heightened STAT3 activity in multiple sclerosis (MS) highlights a critical interaction driving neuroinflammation." (PMID 40755762, 2025). "Our previous studies identified that mice lacking Socs3 in myeloid cells developed a hyper-activated phenotype of macrophages and neutrophils in a pre-clinical model of Multiple Sclerosis." (PMID 37283760, 2023). "Further, multiple sclerosis has been shown to induce an initial increase, followed by a decrease in IL-17 and IFN-γ production, with simultaneous decrease, followed by gradual increase in Axl and suppressor of cytokine signaling 3 (SOCS3) expression." (PMID 32318067, 2020). "SOCS3 is upregulated in peripheral blood leukocytes and there is negative correlation between level of SOCS1 and SOCS3 in multiple sclerosis patients." (PMID 33271810, 2020).
tuberculosis (11 papers, 2013 to 2023). A chronic, recurrent infection caused by the bacterium Mycobacterium tuberculosis. "We concluded that expression of T-cell exhaustion marker SOCS3 was increased in tuberculosis patients during therapy but was only moderately associated with aberrant IL-7 plasma concentrations." (PMID 28582466, 2017). "Because both enzymes are antipodean macrophage effector molecules in Mycobacterium tuberculosis (Mtb) infection, we assessed the relevance of SOCS3 for macrophage activation during experimental tuberculosis using macrophage-specific SOCS3-deficient (LysMcreSOCS3loxP/loxP) mice." (PMID 29176982, 2017). "The increased resistance to M. tuberculosis in stat3fl/fllysm cre mice is mirrored by data showing that mice with SOCS3 deficiency in myeloid cells display reduced resistance to TB and toxoplasmosis." (PMID 29338039, 2018). "IL6, IL10, pSTAT3, and SOCS3 have been identified as influential factors distinguishing tuberculosis patients from healthy individuals." (PMID 37834286, 2023). "Our results showed that active tuberculosis subjects had higher levels of SOCS-3 mRNA, lower expressions of SOCS-2, -4, -5, -6, -7, and cytokine-inducible SH2-containing protein-1 (CIS-1) mRNAs, but not SOCS-1 mRNA than healthy and LTBI subjects." (PMID 28430824, 2017). "Previously, we identified SOCS3 as a marker of CD4+ T cells in tuberculosis, and others described SOCS3 as a central regulator of T-cell exhaustion and target of IL-7 in chronic viral infections." (PMID 28582466, 2017). "Mtb-infected macrophages express Socs3 in a MyD88-dependent manner and during experimental tuberculosis (TB), Socs3 is induced in lungs of infected mice." (PMID 29176982, 2017). "A central role of SOCS3 in tuberculosis is strongly suggested." (PMID 35759173, 2023). "Notably, based on principal component analysis, IL-6, IL-10, pSTAT3, and SOCS3 were the most influential factors that distinguished tuberculosis patients from healthy controls." (PMID 34035497, 2021). "Marginal increased SOCS3 expression was detected in tuberculosis patients prior to therapy (p < 0.16), and significantly increased SOCS3 levels were detected at two months under therapy (p < 0.001) and after six months (p = 0.04) as compared to healthy contacts." (PMID 28582466, 2017). "Our results on SOCS3 and PD-1 expression did not support a major role of T-cell exhaustion in human tuberculosis and this is in accordance with a previous study." (PMID 28582466, 2017). "In this, study we sought to explore the expression of SOCS3 and STAT3 in TB patients in comparison to their healthy contacts when exposed to the wild type mycobacterium tuberculosis." (PMID 35839170, 2022).
Autoimmunity (10 papers, 2014 to 2024). The occurrence of an immune reaction against the organism's own cells or tissues. "The first, cg18181703, is one of three FEV1-associated DMS in SOCS3, which has been associated with infection and autoimmunity, modulates the lung inflammatory response, and JAK-STAT signal transduction." (PMID 30935889, 2019). "The accumulated data suggest a relevant program coordinated by SOCS3 in different cell populations, devoted to the control of immune homeostasis in physiological and pathological conditions such as infection and autoimmunity." (PMID 24600449, 2014). "SOCS3 was found to inhibit the production of IL-1 and IFNγ in vitro, implying that it may influence autoimmunity in T1D." (PMID 37400916, 2023). "The other nodes of the network mainly contain genes/proteins related to autoinflammatory/autoimmunity, such as JAK1, STAT3, STAT5B, IL10RA, and IL10RB, with SOCS3 as a hub." (PMID 39359477, 2024). "In addition, we investigated the combination of SOCS3 deletion and SDF-1 preconditioning on β-cell autoimmunity and allograft rejection." (PMID 37400916, 2023). "The vital role of vitamin D and microbiota in immune responses, including autoimmunity, SOCS1, and SOCS3, have been reported to be involved in Vitamin D metabolism through the VDR-miRNA155-SOCS1 pathway, negatively regulating inflammation and disease pathogenesis." (PMID 38006062, 2023).
Crohn disease (10 papers, 2007 to 2025). A gastrointestinal disorder characterized by chronic inflammation involving all layers of the intestinal wall, noncaseating granulomas affecting the intestinal wall and regional lymph nodes, and transmural fibrosis. "Emerging evidence has implicated epigenetic modifications of SOCS3, particularly promoter methylation in colonic mucosa, as a molecular hallmark of the inflammatory pathology characteristic of Crohn’s Disease." (PMID 40506039, 2025). "Increases in IGF1, accompanied by altered levels of SOCS3, have been associated with smooth muscle hyperplasia in the context of Crohn’s disease." (PMID 36569914, 2022). "In line with our results, miR-19b was also reported to downregulate suppressor of cytokine signaling 3 (SOC3), modulating chemokine production in intestinal epithelial cells and thereby avoiding intestinal inflammation in Crohn’s disease, which may ultimately prevent the derived disease, CRC." (PMID 31339921, 2019).
experimental autoimmune encephalomyelitis (10 papers, 2015 to 2023). An autoimmune demyelinating disease of the central nervous system that is produced experimentally in animals by the injection of homogenized brain or spinal cord in Freund's adjuvant. "In an experimental autoimmune encephalomyelitis model, DHA ameliorated autoimmune inflammation by activating the FFA4 signaling pathway in dendritic cells, which was mediated mechanistically through SOCS3 expression and a downregulation of the JAK-STAT pathway." (PMID 35563671, 2022).
influenza (10 papers, 2014 to 2024). An acute viral infection of the respiratory tract, occurring in isolated cases, in epidemics, or in pandemics; it is caused by serologically different strains of viruses (influenzaviruses) designated A, B, and C, has a 3-day incubation period, and usually lasts for 3 to 10 days. "SOCS1 and SOCS3 expression has been associated with symptomatic influenza infection, whereas SOCS2 and SOCS5 have been linked to asymptomatic disease." (PMID 24809749, 2014). "More broadly, since SOCS3 has been identified as a virulence factor even in severe influenza, it is conceivable that these findings are also relevant to other viral diseases." (PMID 38238298, 2024). "Importantly, inhibition of IL-6 by the suppressor of cytokine signaling 3 (SOCS-3) improves influenza outcomes by reducing inflammation in mice (Liu and others 2019)." (PMID 35674675, 2022). "Thus, IAV-induced high level of SOCS3 is in favor of viral replication and thereby promotes influenza pathogenesis." (PMID 31474976, 2019). "Thus, a virus virulence factor, SOCS3, is expressed at a higher level in the obese, who are at greater risk of the flu than are non-obese individuals." (PMID 33193390, 2020). "So far very little is known regarding the role of different SOCS proteins in influenza infection, outside of the ability of SOCS1 and SOCS3 to regulate specific cytokine receptor complexes." (PMID 24809749, 2014). "IAV infection upregulated SOCS1 and SOCS3, and SOCS1/3 antagonist peptide could protect mice against lethal influenza infection." (PMID 32532301, 2020). "Reduction in SOCS3 mRNA was only seen in the absence of influenza infection (MA+Inf−)." (PMID 31796757, 2019).
Hypertension (9 papers, 2016 to 2026). The presence of chronic increased pressure in the systemic arterial system. "Numerous studies demonstrate the anti-inflammatory effect of SOCS3 in hypertension, obesity and allergic reaction bringing more insights into the role of suppressing inflammation." (PMID 33318871, 2021). "SOCS3 preserves endothelial function in angiotensin II (Ang II) induced hypertension model, suppresses inflammation of macrophages in lipopolysaccharides (LPS) induced model and inhibits proliferation of VSMCs in vein graft restenosis model." (PMID 33318871, 2021). "There was an interaction between the SOCS3, JAK2 and STAT3 genes and hypertension/triglycerides." (PMID 34991691, 2022).
myeloproliferative neoplasm (9 papers, 2013 to 2022). A clonal hematopoietic stem cell disorder, characterized by proliferation in the bone marrow of one or more of the myeloid (i.e., granulocytic, erythroid, megakaryocytic, and mast cell) lineages. "Histone deacetylase inhibitor, that is, sodium butyrate, increases the transcript and protein expression levels of SOCS1 and SOCS3 by triggering the histone acetylation of SOCS1 and SOCS3 gene promoters in myeloproliferative neoplasm." (PMID 28228755, 2017). "In hematopoietic progenitors obtained from myeloproliferative neoplasm patients, Curcumin elevated the transcript levels of Socs1 and Socs3 by inhibiting the histone deacetylase activity." (PMID 25822711, 2015). "Nevertheless, upregulation of SOCS3 has been reported in CTCL and other malignancies in association with elevated JAK-STAT signalling, and in JAK2V617F positive myeloproliferative disorders together with STAT3 and STAT5B, consistent with our findings." (PMID 23372669, 2013). "Thus, SOCS3 methylation occured at high frequency in BCR-ABL-negative chronic myeloproliferative disease (CMPD) and post-CMPD acute myeloid leukemia, as well as chronic lymphoproliferative disease of NK cells (CLPD-NK)." (PMID 34604264, 2021). "In this review, we discuss JAK-STAT signalling pathway inhibition by the inducible inhibitor “suppressor of cytokine signaling 3 (SOCS3), its role in diseases such as myeloproliferative disorders, and its function as part of a multi-subunit E3 ubiquitin ligase complex." (PMID 24886706, 2014).
myocardial infarction (9 papers, 2012 to 2025). Gross necrosis of the myocardium, as a result of interruption of the blood supply to the area, as in coronary thrombosis. "Increased suppressor of cytokine signaling 3 (SOCS3) expression was also associated with increased circulating monocyte–platelet aggregates in women that had a myocardial infarction." (PMID 38139267, 2023). "ANXA3 and SOCS3, as novel biomarkers for acute myocardial infarction (AMI), demonstrates significantly superior diagnostic performance compared to traditional markers CD34 and FLT3, with area under the ROC curve (AUC) exceeding 0.7, highlighting their stronger clinical relevance." (PMID 40760666, 2025). "In a model of myocardial infarction, the application of SOCS3 conditional knockout (SOCS3-CKO) in mice significantly reduced the size of myocardial remodeling." (PMID 37958686, 2023). "Our present results showed that IPC markedly reduced myocardial infarct size after I/R in SOCS3-CKO mice." (PMID 34292971, 2021). "It was also reported that plasma SOCS3 was significantly increased in acute myocardial infarction patients and that acute myocardial infarction patients with a higher plasma SOCS3 level were at higher risk for major adverse cardiac events and worse 5-yr overall survival." (PMID 37160311, 2023). "Therefore, IRI-induced SOCS3 may reduce the effect of cytokine therapy in patients with acute myocardial infarction." (PMID 26010537, 2015). "In SOCS3-CKO mice, IPC substantially reduced the myocardial infarct size (by approximately 90%) after I/R." (PMID 34292971, 2021). "Following I/R, IPC substantially reduced myocardial infarct size and significantly enhanced STAT3 phosphorylation in SOCS3-CKO mice compared to in WT mice." (PMID 34292971, 2021). "We have shown up-regulation of SOCS3 and FAM20 genes in the first 4–6 days of myocardial infarction." (PMID 23185530, 2012). "Up-regulation of SOCS3 and FAM20 genes in the first days of myocardial infarction is observed in the vast majority of patients." (PMID 23185530, 2012). "Highly significant and substantial upregulation of SOCS3 and FAM20 genes expression in the first 4–6 days of myocardial infarction in all patients is the most robust observation of our work." (PMID 23185530, 2012). "SOCS3 expression can occur in response to cytokine-triggered STAT3 signaling or H2O2 and likely contributes to proteasomal degradation and cardiac remodeling, e.g., after myocardial infarction." (PMID 39335522, 2024). "As we previously reported, SOCS3-CKO mice without IPC exhibited a significantly reduced myocardial infarct size compared to WT mice without IPC." (PMID 34292971, 2021).
allergic asthma (8 papers, 2011 to 2025). A asthma with a basis in a pathological type I hypersensitivity reaction. "Using different in vitro and in vivo techniques, we recently demonstrated that SOCS3-siRNA intranasal delivered in a mouse model of chronic allergic asthma leads to inhibition of the asthmatic response." (PMID 25764157, 2015). "Supporting this idea, there is a study that states that local inhibition of the STAT-3/STAT-5/SOCS3 dependent feedback loop has been shown to suppress experimental allergic asthma." (PMID 24637581, 2014). "In a murine model of chronic allergic asthma, the intranasal administration of a commercially designed suppressor of cytokine signaling 3 (SOCS3) siRNA resulted in the attenuation of airway inflammation and remodeling by reducing eosinophilia, mucus secretion, and airway hyperresponsiveness." (PMID 40722500, 2025). "Previously, transgenic expression of SOCS3 in T cells resulted in increased Th2 cell production, airway eosinophilia, and airway hyper-responsiveness (AHR) in a murine model of OVA-allergic asthma." (PMID 24637581, 2014). "The STAT3/SOCS3 and mitogen activated-protein kinase (MAPK) pathways can mediate allergic asthma." (PMID 40005151, 2025). "The role of the SOCS3 gene in inflammatory diseases, such as allergic asthma, has not been well defined." (PMID 32807859, 2020).
bladder cancer (8 papers, 2018 to 2025). "To validate whether NSUN2 and SOCS3 still plays a similar role in BC patients, we isolated TAMs from human bladder cancer specimens with FACS described as above." (PMID 41354740, 2025). "ACOX1 can be combined with MMP1, suppressor of cytokine signaling 3 (SOCS3) to diagnose oral squamous cell carcinoma (OSCC), and downregulation in bladder cancer might be due to PDK1 down-regulation, suggesting that it might serve as a potential biomarker and therapeutic target for bladder." (PMID 37724116, 2023). "This was confirmed in bladder cancer for Janus kinase (JAK) signaling pathway, where negative regulator of JAK-SOCS3 (suppressor of cytokine signaling 3) was reduced, with simultaneous upregulation of miR-221 (micro RNA), leading to enhanced cell apoptosis, and attenuated cell proliferation." (PMID 32392774, 2020).
depression (8 papers, 2019 to 2024). "Among these genes were SOCS3 (FDR = 0.0039) and PROK2 (FDR = 0.0028), which have previously both been linked to depression." (PMID 33833401, 2021). "The STAT3/SOCS3 pathway has been suggested to be involved in the pathogenesis of depression." (PMID 33833401, 2021). "Interestingly, the inhibition of EZH2 in a depression model elevated the expression of SOCS3, which suggested that SOCS3 might regulate microglial activation in depression." (PMID 35230663, 2022). "In the present study, we revealed the expression of two downstream genes, NRF2 and SOCS3, was inhibited by the GAS5/EZH2 axis in the depression model." (PMID 35230663, 2022). "Rg1 consistently increased the expression of SOCS3 and NRF2 in the depression model, whereas the GAS5 overexpression compromised this effect, as indicated by a notable decrease in the expression of SOCS3 and NRF2." (PMID 35230663, 2022). "Induction of nuclear factors Nrf2, SOCS3/STAT3, and inhibition of apoptosis may also be involved in the Zn and Se neuroprotective effect on memory recovery and prevention of anxiety/depression-like behavior on a long-term post-reperfusion." (PMID 38707461, 2024).
lymphoma (8 papers, 2013 to 2024). A malignant (clonal) proliferation of B- lymphocytes or T- lymphocytes which involves the lymph nodes, bone marrow and/or extranodal sites. "We tested if the transcriptional levels of SOCS1 (the only regulator reported in the literature to be associated with inhibition of IL-10 signaling in a lymphoma cell line) and SOCS3 (as control; it does not inhibit IL-10R) were increased by IFN-β treatment." (PMID 30061883, 2018). "First, SOCS6 could inhibit antitumor immunity by suppressing effects of IFN-alpha, as described for SOCS3 in T lymphoma." (PMID 28924457, 2017). "In this study, CD37 has been discovered to interact with suppressor of cytokine signaling 3 (SOCS3), and its absence was hypothesized to drive lymphoma development through constitutive activation of the IL-6 signaling pathway." (PMID 33333768, 2020).
multiple myeloma (8 papers, 2017 to 2021). "One of the best characterized pathways in this regard is the downregulation of the JAK2/STAT3 signaling pathway by increased SOCS3 expression, as described in multiple myeloma." (PMID 34204116, 2021). "OncomiR-19a, as a biomarker, may induce better responsiveness to BTZ in myeloma cell lines through itstargets SOCS3, STAT3 and PTEN." (PMID 34837676, 2021). "The rate of apoptosis inthe myeloma cells after BTZ treatment considerably increased, which indicated an increase in the mRNA of SOCS3, PTEN, BCL-2, and CDKN1." (PMID 34837676, 2021). "Previous studies have shown that SOCS3 inhibits the JAK2/STAT3 pathway in hepatocyte and multiple myeloma cells." (PMID 34765550, 2021). "Additionally, work on myeloma cell lines showed that B7-H3 activates STAT3, subsequently promoting cell proliferation, by encouraging the degradation of SOCS3, a known inhibitor of STAT3 phosphorylation." (PMID 32992699, 2020). "Similarly, in multiple myeloma patients, methylation of SOCS3 was found in 5 of the 70 cases but none in the control group." (PMID 28404963, 2017).